CCL2 (C-C motif chemokine ligand 2)
Diseases named in the same sentence as CCL2 in open-access papers (continued):
Sharing a sentence is not in itself a finding about the gene and the disease.
movement disorder (2 papers, 2019 to 2025). Neurological conditions resulting in abnormal voluntary or involuntary movement, which may impact the speed, fluency, quality and ease of movement. "Down-regulating CCL2 in vivo was found to markedly relieve MPTP-induced movement disorder and spatial memory deficits and to play neuroprotective and anti-inflammatory roles in MPTP-induced PD mice." (PMID 30761072, 2019).
musculoskeletal diseases (2 papers, 2023 to 2025). "Therefore, the clinical benefit of CCL2 blockade in mitigating inflammation in musculoskeletal diseases is still controversial." (PMID 37457301, 2023).
neurodevelopmental disorder (2 papers, 2021 to 2025). A behavioral and cognitive disorder with onset during the developmental period that involves impaired or aberrant development of intellectual, motor, or social functions. "Specifically, cytokine and chemokine profiles alteration, which is derived from CCL2, CCL7, and CCL11 imbalance in our patients, may provoke this neurodevelopmental disorder." (PMID 34828266, 2021).
CCL2 also shares sentences with these, for which no sentence is quoted: hyperuricemia (21 papers); multiple myeloma (21); sarcopenia (18); arteriosclerosis (17); Abdominal obesity (13); polycystic ovary syndrome (13); acute myocardial infarction (12); non-alcoholic fatty liver disease (12); hyperhomocysteinemia (11); glomerulopathy (10); septic shock (10); vitamin D deficiency (10); acute lung injury (9); intracranial aneurysm (9); proliferative diabetic retinopathy (9); Atherosclerotic lesion (8); diffuse large B-cell lymphoma (8); Impaired glucose tolerance (8); macular holes (8); Multiple Organ Failure (8); prediabetes (8); appendicitis (7); bacteremia (7); lipid metabolism disorders (7); open-angle glaucoma (7); pulmonary edema (7); retinal ischemia (7); adenomyosis (6); autism spectrum disorder (6); chronic periodontitis (6).
A further 523 diseases each share a sentence with CCL2 in 6 papers or fewer.